BICDL2 (BICD family like cargo adaptor 2)
Synonyms: BICDR-2; BICDR2; CCDC64B
Tractability: No criterion of Open Targets' tractability assessment is met for any kind of drug.
Gene: Protein-coding gene on chromosome 16 (3,027,682 to 3,036,993, reverse strand). Ensembl gene ENSG00000162069.
Subcellular location (Human Protein Atlas): Actin filaments; Cytosol; Intermediate filaments
Gene Ontology:
Molecular function: protein binding; small GTPase binding
Biological process: Golgi to secretory granule transport; vesicle transport along microtubule
Genetic constraint (gnomAD): Loss-of-function variants: 62 observed, 38.31 expected, observed/expected ratio (o/e) 1.62, 90% interval 1.31 to 1.92. The synonymous counts are far from expectation, so gnomAD's model fits this gene poorly and the ratio says little. Missense variants: 808 observed, 558.4 expected, observed/expected ratio (o/e) 1.45, 90% interval 1.37 to 1.53. Synonymous variants: 358 observed, 247.43 expected, observed/expected ratio (o/e) 1.45, 90% interval 1.33 to 1.58.
Homologues: Orthologues: chimpanzee BICDL2 (99% identical), macaque BICDL2 (96% identical), dog BICDL2 (87% identical), pig BICDL2 (86% identical), guinea pig BICDL2 (86% identical), rat Bicdl2 (86% identical), mouse Bicdl2 (84% identical), tropical clawed frog bicdl2 (32% identical), zebrafish bicdl2 (29% identical), Drosophila melanogaster CG32137 (29% identical). Paralogues in human: BICDL1 (35% identical), SPDL1 (16% identical).
Diseases named in the same sentence as BICDL2 in open-access papers:
BICDL2 is named in the same sentence as 3 diseases in open-access papers, as found by Europe PMC text mining. Sharing a sentence is not in itself a finding about the gene and the disease. The quoted sentences say what the papers report.
infection (1 paper, 2024). The state of being infected such as from the introduction of a foreign agent such as serum, vaccine, antigenic substance or organism. "Using immunofluorescence staining, we confirmed the recruitment of NINL and BICDL2 to Shigella infection foci (possibly on the IAMs) at 30 min post-infection (respectively)." (PMID 38316786, 2024).
BICDL2 also shares sentences with these, for which no sentence is quoted: hepatocellular carcinoma (1 paper); tumour (1).